RB1 (RB transcriptional corepressor 1)
Diseases named in the same sentence as RB1 in open-access papers (continued):
Sharing a sentence is not in itself a finding about the gene and the disease.
ovarian carcinoma (continued). "To address this hypothesis, we have comprehensively evaluated the clinicopathological significance of the CDK2, CDK4, CDK6, cyclin D1, cyclin E1, RB1 and pRB1(Ser 795) protein expression in a clinical cohort of epithelial ovarian cancer." (PMID 38612869, 2024). "Moreover, CXCR4, IFNG, IL24, MTMR14, and RB1 all exhibited higher expression in ovarian cancer compared to normal specimens." (PMID 33748162, 2021). "HDAC1, PEX3, MTMR14, and RB1 had the moderate intensity and high quantity in ovarian cancer." (PMID 33748162, 2021). "Furthermore, IFNG, IL24, MTMR14, and RB1 were highly expressed in ovarian cancer than normal tissues." (PMID 33748162, 2021). "Another example of a gene commonly inactivated by structural variants is RB1, an important biomarker of resistance to CDK4/6 inhibitors such as palbociclib, with this class of event contributing to 47% and 43% of RB1 inactivation in breast and ovarian cancer respectively." (PMID 33144218, 2020). "However, 17% of ovarian cancer patients in the TCGA database also have homozygous deletions or significantly downregulated RB1; these patients are less likely to receive significant benefit from CDK4/6 inhibitor therapy." (PMID 29644000, 2018). "Moreover, our approach selected new genes, such as AKT3 and RB1, which are also related to ovarian cancer." (PMID 27378931, 2016). "Notably, all four short variants of RB1 under LOH exhibited pCR, which is intriguing given a report demonstrating that RB1 loss is associated with tumors that are extremely sensitive to platinum retreatment in ovarian cancer." (PMID 38869771, 2024). "However, a recent biomarker study in patients with ovarian cancer treated with atezolizumab or placebo and standard chemotherapy found that deleterious mutations in RB1 were prognostic for a better PFS, regardless of the addition of atezolizumab." (PMID 38837893, 2024). "In drug‐sensitive recurrent ovarian cancer patients, MYC had the highest frequency of copy number variations (3/11, 27%), followed by RB1 (2/11, 18%), and PTK2 (2/21, 10%)." (PMID 29797793, 2018). "The mutation frequencies for NF1, RB1, and KIT in our BM samples were not in the range described for ovarian cancer specimens, they were less frequent." (PMID 28497333, 2017).
sarcoma (73 papers, 1989 to 2025). A usually aggressive malignant neoplasm of the soft tissue or bone. "Afterward, genetic alteration of the Rb1 locus was associated with the development of various types of cancer, including sarcoma, lung and ovarian cancer." (PMID 35267571, 2022). "The predisposition to sarcomas has been attributed to genetic susceptibility due to inactivation of the RB1 gene as well as to the genotoxic effect of radiotherapy applied to treat Rb." (PMID 33375764, 2020). "In tumors such as prostate, bladder, and sarcoma the single copy loss is focused over the RB1 locus with deletion occurring at reasonably high levels." (PMID 32242058, 2020). "Analyses revealed that the tumors not only harbored mutations characteristic of sarcoma, such as RB1 (50%), ATRX (38%), and FBXW7 (17%) mutations, but also possessed mutations commonly associated with endometrial adenocarcinoma, including PTEN (42%), PIK3CA (42%), and AKT (17%) mutations." (PMID 41181577, 2025). "In general, murine sarcomas with Rb1 nullizygosity were associated with the undifferentiated morphology, except for one case identified as aRMS which also showed lower expression of COL18A1, COL4A1, and PLOD2 compared to Rb1 wildtype sarcomas (p = 0.0035, 0.04, and 0.08, respectively)." (PMID 33708626, 2021). "We further investigated the genomic alterations that may influence tumor infiltration by leukocytes including RB1 loss in undifferentiated pleomorphic sarcomas and ELK3 amplification in dedifferentiated liposarcomas." (PMID 33980253, 2021). "There is on-going research to try to identify whether specific RB1 mutations or location of mutations predispose to sarcomas, which could lead to identification of those survivors at greatest risk." (PMID 23036192, 2012). "However, the risk for bone sarcomas and STS remains, reflecting the genetic predisposition to these sarcomas due to loss of heterozygosity in the RB1 gene." (PMID 23036192, 2012).
sarcoma (continued). "RB1, a gene classified as a driver in sarcoma by COSMIC, is also well connected in our solution, linking protein kinase C inhibitor staurosporine to the seed genes MYC, SKP2 and DNMT3A." (PMID 35580047, 2022). "The Rb1 nullizygous sarcomas had a significantly lower number of tumors expressing COL18A1, COL4A1, and PLOD2." (PMID 33708626, 2021). "Whereas, those in ALT-related pathways, such as RB1 in LMS sarcomas, likely promote ALT-mediated telomere maintenance." (PMID 33924498, 2021). "This assumption was also encouraged by the fact that RCBTB1 is located in the 13q14 region, which comprises RB1, a well-known tumor suppressor and among the most frequently altered gene in those sarcomas." (PMID 30641971, 2019). "Loss of regions in chromosome 13 is a frequent finding in other types of sarcomas as well, and the well-known tumour suppressor gene RB1 is considered to be the prime candidate target for the deletion involving the 13q14 region." (PMID 21085701, 2010). "Two of these, both leiomyosarcomas, contained a chromosomal breakpoint within the RB1 gene, while in the third tumour, a radiation induced sarcoma, complete deletion was observed." (PMID 2765366, 1989). "Additionally, RB1 has been linked to cytokine production by fatty acid oxidation and AMP-activated protein kinase (AMPK) in sarcoma and breast cancer." (PMID 40707487, 2025). "The Cancer Genome Atlas (TCGA) data suggest UHRF1 is significantly overexpressed in malignancies that frequently present RB pathway inactivation including sarcomas, breast invasive carcinomas, and lung adenocarcinomas, but not in cancers where RB1 loss is infrequent, like prostate adenocarcinomas." (PMID 36068209, 2022). "Regarding other frequently altered genes in sarcomas, one copy of chromosome 13 carrying RB1 was lost only in S2012B and S2016A and one copy of PTEN was lost only in S2008 and S2016A, indicating that these alterations were probably not the primary genetic alterations." (PMID 33963205, 2021). "RB1 downregulation may present an immune evasion mechanism in sarcomas particularly of relevance in LMS, which are almost invariably characterized by loss of RB1 function." (PMID 33980253, 2021).
sarcoma (continued). "A more aggressive, undifferentiated morphology was associated with the Rb1 nullizygous mouse sarcomas and was not seen in eRMS subtypes." (PMID 33708626, 2021). "However, some of the sarcomas may carry promoter methylation of RB1 and/or CDKN2A, resulting in the inactivation of either gene that is not identified by the NGS." (PMID 33924080, 2021). "The RB1 deletion occurred in 21.4% of CKS patients and 9.7% of TCGA sarcoma patients (P = 0.76, t-test)." (PMID 30598078, 2018). "The lack of RB1 sequencing at baseline and the challenge of obtaining tumor biopsy for genomic screening purposes in the context of advanced sarcoma patients, additionally hindered by the SARS-CoV2 pandemic, have been limitations of the trial." (PMID 37875500, 2023). "Since CD34 is a marker for lipomas and lipoma-like sarcomas, further analysis of SCL typically shows negative staining for desmin, RB1, MDM2, and SMA." (PMID 40980795, 2025). "The 33 novel fusions were identified in 21 patients involving RB1, BCL2, and BRCA2; none were identified in patients with TRS, and 21 (21.0%) were identified in patients with genomically complex and other sarcomas (p < 0.001)." (PMID 40755265, 2025). "This does not challenge the major and indisputable role of RB1 in pleomorphic sarcoma oncogenesis, but rather suggests that, in our cohort, the prognostic value of RCBTB1 is independent of RB1 status." (PMID 30641971, 2019). "In addition, 33 novel gene fusions involving RB1, BCL2, and BRCA2 were identified in 21 patients, predominantly in genomically complex and other sarcomas, not in TRS." (PMID 40755265, 2025). "The fact that RCBTB1 and RB1 have antagonistic roles in cell growth and are frequently co-deleted, as in 50% of our 106 sarcomas, suggests that RCBTB1 may not be just a passenger gene affected by RB1 deletion." (PMID 30641971, 2019).
lung adenocarcinoma (70 papers, 2010 to 2026). A carcinoma that arises from the lung and is characterized by the presence of malignant glandular epithelial cells. "In lung adenocarcinoma, RB1 deletion or mutation is rare but becomes prevalent in transformed SCLC, facilitating neuroendocrine differentiation." (PMID 40134592, 2025). "To better understand the roles of RB in lung adenocarcinoma development, we developed the RbXTR allele which allows reversible Rb1 inactivation in the KP lung adenocarcinoma model." (PMID 37728504, 2023). "In the untreated EGFR‐mutated lung adenocarcinomas (LuADs), RB1 is excessively altered by inactivation, mainly through complex intragenic rearrangements." (PMID 34799997, 2022). "Lung adenocarcinomas (LUAD) with loss of RB1 were more likely to transform into SCLC after treatment, supporting the role of RB1 loss in lineage switching." (PMID 34145257, 2021). "For instance, RB1 is rarely found mutated in lung adenocarcinomas whereas p16INK4a, an upstream activator of the RB1 protein and the two related proteins p107 and p130, is frequently inactivated in this tumor type." (PMID 21532835, 2010). "RB1 inactivation was believed to be responsible for the transformation of EGFRm lung adenocarcinoma to SCLC following EGFR TKIs, similar to de-novo SCLC." (PMID 35268520, 2022). "Genomic data analyses evidenced that EGFR and KRAS mutations, the most common aberrations in lung adenocarcinoma, are extremely rare in pure SCC, while alterations in the FGFR kinase family, PIK3CA, CDKN2A and RB1 pathways are common." (PMID 35743191, 2022). "According to prior study, irreversible defects in RB1 tumor suppressor functions often predict poor outcomes in many human cancers, such as lung adenocarcinoma." (PMID 36167504, 2022). "Although mutations of RB1 are rare in lung adenocarcinomas, CDKN2A, the gene encoding p16INK4a the upstream activator of the pRB pathway is a frequently targeted for mutation." (PMID 23936539, 2013).